PICK1 (protein interacting with PRKCA 1)
Diseases named in the same sentence as PICK1 in open-access papers (continued):
Sharing a sentence is not in itself a finding about the gene and the disease.
infertile (2 papers, 2022 to 2023). "Whole-exome sequencing (WES) was performed on 20 infertility patients with oligozoospermia to identify pathogenic PICK1 mutations." (PMID 38001535, 2023). "The present work was aimed to use multi-omics analysis to research the effects of PICK1 deficiency on Sertoli cells and to identify effective biomarkers to distinguish fertile males from infertile males caused by PICK1 deficiency." (PMID 38001535, 2023). "In this study, two rare deletion mutations in PICK1 were identified in infertility patients by Whole-exome sequencing (WES)." (PMID 38001535, 2023). "Clinical tests have shown that infertile men carrying PICK1 deletion mutations have a specific decrease in serum inhibin B levels secreted by Sertoli cells, which is synthesized in the Golgi apparatus." (PMID 38001535, 2023). "Systematic multi-omics analysis of PICK1 knockout mouse indicated that infertility caused by PICK1 deficiency could be attributed to vesicle secretion dysfunction in Sertoli cells." (PMID 38001535, 2023). "Two loss-of-function deletion mutations c.358delA and c.364delA in PICK1 resulting in transcription loss of BAR functional domain were identified in infertility patients with a specific decrease in serum inhibin B, indicating functional impairment of Sertoli cells." (PMID 38001535, 2023). "The results showed that PICK1 interacted with 25 definitive infertility genes and 15 strong infertility genes." (PMID 38001535, 2023). "PICK1 has been studied in mice models, where PICK1 knockout mice were infertile, with reduced sperm count, severely impaired motility, and fragmented structure of the acrosomes." (PMID 35774118, 2022).
ischemia (2 papers, 2013 to 2020). A hypoperfusion of the BLOOD through an organ or tissue caused by a PATHOLOGIC CONSTRICTION or obstruction of its BLOOD VESSELS, or an absence of BLOOD CIRCULATION. "To directly test whether the manipulation of the Arp2/3-complex machinery can influence injury-associated changes in astrocyte morphology, we knocked down PICK1 using siRNA and exposed these cells to oxygen and glucose deprivation (OGD), an in vitro model for ischemia." (PMID 23843614, 2013).
neuropathic pain (2 papers, 2020 to 2024). Chronic pain caused by damage to nerve fibers. "We recently published on a TAT-conjugated, bivalent, high-affinity PICK1 inhibitor (TPD5) displaying robust efficacy in the SNI model of neuropathic pain and CFA model of inflammatory pain following i.t. administration in mice." (PMID 39287978, 2024).
peripheral nerve injury (2 papers, 2011 to 2021). Injury to a peripheral nerve. "Targeted disruption of PICK1 gene did not affect basal paw withdrawal responses to acute noxious thermal and mechanical stimuli or locomotor reflex activity, but it completely blocked the induction of peripheral nerve injury-induced mechanical and thermal pain hypersensitivities." (PMID 21291534, 2011).
amyotrophic lateral sclerosis (1 paper, 2013). Amyotrophic lateral sclerosis (ALS) is a neurodegenerative disease characterized by progressive muscular paralysis reflecting degeneration of motor neurons in the primary motor cortex, corticospinal tracts, brainstem and spinal cord. "This hypothesis is supported by the recent description of elevated levels of PICK1 in reactive astrocytes in an animal model of amyotrophic lateral sclerosis (ALS)." (PMID 23843614, 2013).
bone metastasis (1 paper, 2022). Transfer of a neoplasm from its primary site to bones. "In metastatic prostate cancer, a decrease of PICK1 expression in the cancer tissue with bone metastasis was observed." (PMID 35774118, 2022).
cocaine dependence (1 paper, 2020). A psychologically and socially impaired state, with or without physiological changes, that develops as a result of using cocaine and which leads to compulsive behaviors to acquire the substance. "In this context, expression of calcium permeable (CP) AMPARs in the process of homeostatic scaling as well as in maladaptive plasticity associated with cocaine addiction and oxygen–glucose depletion has been shown to involve PICK1." (PMID 32352640, 2020). "In analogy, PICK1 seems to serve a specific role in potentiating AMPAR function during acquisition and reacquisition of cocaine dependence, suggesting that PICK1 is a promising target in addiction." (PMID 32352640, 2020).
cognitive decline (1 paper, 2018). "They found that patients with rs2076369 GT heterozygotes showed better performance than TT homozygotes, suggesting the association between PICK1 gene SNPs and cognitive decline in schizophrenic patients." (PMID 30687223, 2018).
gastric carcinoma (1 paper, 2024). A carcinoma that arises from epithelial cells of the stomach. "Other studies have demonstrated that PICK1 expression is significantly reduced in gastric tumor tissues, which has a negative impact on the overall survival of patients with gastric carcinoma." (PMID 38664379, 2024).
hepatocellular carcinoma (1 paper, 2013). A malignant tumor that arises from hepatocytes. "There is also evidence suggesting that activation of erythropoietin-producing hepatocellular carcinoma (Eph) receptors decreases interaction between Eph–PICK1 and instead favors the SR–PICK1 interaction, resulting in a subsequent increase in D-serine synthesis in cultured hippocampal astrocytes." (PMID 23630460, 2013).
injury (1 paper, 2021). Damage inflicted on the body as the direct or indirect result of an external force, with or without disruption of structural continuity. "FSC231, a PICK1-specific inhibitor, aggravated LPS-induced kidney injury." (PMID 34307672, 2021).
liver cancer (1 paper, 2023). An epithelial or non-epithelial malignant neoplasm that arises from the liver. "100μmol/L luteolin inhibits the proliferation of liver cancer cells by down-regulating the miRNA expression of the proliferation-related genes LETM1, URG11, PICK1, and CyclinD1 in HepG2 liver cancer cells, suggesting that luteolin may inhibit cell proliferation." (PMID 37151401, 2023).
metabolic syndrome (1 paper, 2013). A cluster of metabolic risk factors for CARDIOVASCULAR DISEASES and TYPE 2 DIABETES MELLITUS. "To study the involvement of PICK1 in a mammalian model of metabolic syndrome, we used adult (18-wk-old) male mice fed a 60% high-fat diet for 12 wk." (PMID 23630454, 2013). "Summarized, PICK expression appears sensitive to metabolic changes that characterize metabolic syndrome and/or T2D; hence, it is possible that PICK1 plays a role in the pathophysiological process of metabolic diseases or in a protective compensatory mechanism." (PMID 23630454, 2013). "Thus, PICK1 expression is both in flies and mice sensitive to changes in metabolic states that mimic the human metabolic syndrome." (PMID 23630454, 2013).
methamphetamine dependence (1 paper, 2021). A drug dependence that is a psychological dependency on the regular use of methamphetamine. "Showing a possible association between PICK1-rs713729 and PICK1-rs2076369 in the PICK1 gene promoter with methamphetamine dependence were the key findings of the present study." (PMID 33499851, 2021). "In this line, protein that interact with C-kinase-1 (PICK1) and brain-derived neurotrophic factor (BDNF) genes are linked to methamphetamine dependence (substance use disorder)." (PMID 33499851, 2021). "Collectively, the variation in the PICK1 gene was associated with methamphetamine dependence (SUD), reflecting the underlying biological mechanisms, which can make a bridge between pathways and methamphetamine dependence (SUD)." (PMID 33499851, 2021). "Therefore, we aimed to investigate the association between PICK1 and BDNF main SNPs and methamphetamine dependence (substance use disorder (SUD)) in a cohort of Iranian individuals." (PMID 33499851, 2021). "Thus, in a case–control study, we investigated the association between polymorphisms of PICK1 and BDNF genes and methamphetamine dependence in an Iranian population." (PMID 33499851, 2021).
myocardial infarction (1 paper, 2024). Gross necrosis of the myocardium, as a result of interruption of the blood supply to the area, as in coronary thrombosis. "Suppression of Pick1 in macrophages potentiates Smad3 signalling and enhances efferocytosis, minimizing heart necrosis in rats with myocardial infarction." (PMID 38865332, 2024).
neuralgia (1 paper, 2021). "This study provides new experimental data on the mechanism of FSC231's analgesic action in PTL‐induced neuralgia by inhibiting PICK1." (PMID 34582111, 2021). "The expression level of PICK1 in dorsal root ganglion (DRG) of rats was changed by vector plasmid, and the effect of PICK1 on paclitaxel (PTL)‐induced neuralgia of rats was observed in collaboration with FSC231 treatment." (PMID 34582111, 2021).
psychosis (1 paper, 2021). "Additionally, they revealed that PICK1-rs713729 was linked to those with spontaneous relapse of psychosis." (PMID 33499851, 2021).
teratozoospermia (1 paper, 2021). "It should be stressed that the lack of genetic variants of SPATA16 and PICK1 we observed could be due to the small caseload caused by the rarity of this monomorphic teratozoospermia." (PMID 34209343, 2021).
viral infection (1 paper, 2016). "Western blotting analysis confirmed that after viral infection, endogenous syntabulin expression was successfully knocked down and YFP-tagged PICK1 was expressed." (PMID 26868290, 2016).
Waardenburg-Shah syndrome (1 paper, 2025). Waardenburg-Shah syndrome (WSS) is a neurocristopathy characterized by the association of Waardenburg syndrome (sensorineural hearing loss and pigmentary abnormalities) and Hirschsprung disease. "Hence, genomic deletions involving Sox10-E1 and Sox10-E2 would perturb not only SOX10, but also PICK1 and other genes, and may cause a pathology that is more complex than that of conventional Waardenburg-Shah syndrome that results from SOX10 coding mutations." (PMID 40644525, 2025).
cancer (11 papers, 2013 to 2025). A tumor composed of atypical neoplastic, often pleomorphic cells that invade other tissues. "Decreased expression of PICK1 regulates the metastasis of cancer cells and is associated with EndMT." (PMID 36718590, 2023). "The findings show the interplay between VIM, miR‐615‐3p, and PICK1 and open new avenues for targeted cancer therapy." (PMID 39781570, 2025). "Cancer: several studies have observed altered PICK1 expression in human cancers, but the results have been somewhat conflicting." (PMID 35455935, 2022). "PICK1 has been recently suggested to be a valuable drug target for the treatment of neurological disorders, including excitotoxicity, cancer, and neuropathic pain, through its PDZ binding domain." (PMID 33946313, 2021). "Taken together, these correlative and functional data suggest that PICK1 may also play a protective role in preventing cancer progression, and consequently PICK1 inhibitors should be tested for their effect on TGFβ signaling and EMT." (PMID 35455935, 2022). "The involvement of PICK1 in tumorigenesis has been suggested in several human cancers." (PMID 32336285, 2020). "Vimentin affects the miR‐615‐3p‐PICK1 axis via APA, highlighting its role in cancer progression in TNBC." (PMID 39781570, 2025). "Opened up new avenues for targeted cancer therapy, with a focus on regulating the interaction between APA and miR‐615‐3p‐PICK1." (PMID 39781570, 2025). "Pick1 was reported to be the negative regulator of TGF‐beta signaling and inhibit the EMT process and cancer metastasis." (PMID 39781570, 2025). "This study reveals that vimentin affects the miR‐615‐3p‐PICK1 axis through APA, revealing the key role of VIM in cancer progression." (PMID 39781570, 2025). "Notably, cancer patients with significantly reduced levels of PICK1 in their tumors experienced shorter overall survival (OS), progression-free survival (PFS), and distant metastasis-free survival (DMFS) than those with higher levels of PICK1." (PMID 38664379, 2024). "Additionally, the siRNA-mediated knock down of PICK1 in MDA-MB-231 cells decreased cell proliferation and colony formation in vitro and inhibited tumorigenicity in nude mice, presenting PICK1 as a putative target in cancer." (PMID 35455935, 2022).
tumor (6 papers, 2020 to 2024). "PICK1 was reported to involve in regulating the cell to cell junction in epithelial cells, which was associated with tumor invasion and metastasis." (PMID 37179366, 2023). "The tumor-promoting role of miR-615-3p is linked to its ability to directly target 3′-UTR of PICK1." (PMID 32336285, 2020). "Next, to study the tumor growth-related effects of PICK1 in vivo, we subcutaneously injected NPC cells into nude mice." (PMID 38664379, 2024). "Consistent with the in vitro results, PICK1 knockdown stimulated the growth of xenografts compared to controls, whereas xenografts overexpressing PICK1 exhibited slower growth and decreased tumor weight compared to control xenografts." (PMID 38664379, 2024). "Forced PICK1 expression suppresses tumor growth and lung metastasis in NPC cells, while the depletion of PICK1 promoted tumor growth and lung metastasis." (PMID 38664379, 2024). "Our findings indicated that the xenograft tumor tissues produced by PICK1-knockdown cells exhibited a considerably elevated Ki-67-staining score, compared to that of the control cells." (PMID 38664379, 2024). "Conversely, xenograft tumor tissues established using PICK1-overexpressing cells showed the opposite effect." (PMID 38664379, 2024). "Conversely, PICK1 overexpression resulted in its lower expression β-catenin in tumor tissues." (PMID 38664379, 2024). "Recent studies have highlighted that PICK1 plays a role as a tumor suppressor." (PMID 38664379, 2024). "They support PICK1 as a potential tumor suppressor and prognostic marker for NPC." (PMID 38664379, 2024). "Our findings revealed that PICK1 was mutated in every sample in the group with distant metastases, suggesting that it may play a crucial role in NPC tumor progression." (PMID 38664379, 2024). "For PICK1, current understanding of its role in tumor is still limited." (PMID 37179366, 2023). "PICK1 (Protein Interacting With PRKCA 1) codes for a protein which interacts with protein kinase C alpha (PRKCA), and it has been identified as a tumour suppressor gene in astrocytic tumours." (PMID 35774118, 2022). "The genes PICK1 and PSCA are also both thought to play tumour suppressing roles in astrocytic and gastric epithelial cell cancers, respectively." (PMID 35774118, 2022). "Among these genes, PKM, CAV1, GLI3, PICK1, PRPF6, and UBE3A have been identified as oncogenes, and play a pivotal role in orchestrating tumor-host interactions, fostering tumor growth, promoting metastasis, enhancing resistance to therapy, and ensuring cellular survival." (PMID 38280969, 2024).
neurological disease (4 papers, 2018 to 2023). "Lack of potent, selective inhibitors of the PICK1 PDZ domain has hindered efforts at exploring the PICK1-GluA2 interaction as a therapeutic target for neurological diseases." (PMID 30194389, 2018). "Over the past two decades, the functions of PICK1 have been widely discussed in neurological disease and nonneurological disease." (PMID 30402043, 2018).
neurodegenerative disease (2 papers, 2018 to 2022). A disorder of the central nervous system characterized by gradual and progressive loss of neural tissue and neurologic function. "We planned to block the PICK1‐GluA2 protein–protein interaction with a small molecule inhibitor to stabilize surface AMPA receptors as a therapeutic possibility for neurodegenerative diseases." (PMID 29280296, 2018). "The PICK1 PDZ domain has been proposed as a possible drug target because the interactions between the PICK1 PDZ domain and the GluA2 subunit of the AMPA receptor have been shown to progress neurodegenerative diseases." (PMID 35954295, 2022).
metabolic disease (1 paper, 2013). A congenital disorder (due to inherited enzyme abnormality) or acquired (due to failure of a metabolically important organ) disorder resulting from an abnormal metabolic process. "Because of the severe endocrine dysfunction and changed metabolic homeostasis that we observe in PICK1-deficient mice, we tested whether PICK1 expression might be altered in two metabolic disease models, one in flies and one in mice." (PMID 23630454, 2013). "Summarized, our results suggest a hitherto unknown key role of PICK1 and ICA69 in secretory vesicle formation at the TGN and indicate a putative role of PICK1 during metabolic disease." (PMID 23630454, 2013).
PICK1 also shares sentences with these, for which no sentence is quoted: acute kidney injury (2 papers); memory impairment (2); acute lung injury (1); autism spectrum disorder (1); brain arteriovenous malformations (1); brain tumor (1); cocaine abuse (1); colorectal cancer (1); frontotemporal lobar degeneration (1); gastric tumor (1); herpes simplex (1); Histiocytosis (1); Insulin resistance (1); Intellectual disability (1); kidney injury (1); lung carcinoma (1); Lysosomal disease (1); melanoma (1); metastatic prostate carcinoma (1); nasopharyngeal carcinoma (1); nevus (1); oral squamous cell carcinoma (1); ovarian carcinoma (1); rubella (1); sarcoma (1); tauopathies (1).